RNU6-982P (RNA, U6 small nuclear 982, pseudogene)
Gene: Small nuclear RNA gene on chromosome 19 (53,745,004 to 53,745,105, reverse strand). Ensembl gene ENSG00000252025.
Homologues: Orthologues: guinea pig U6 (75% identical). Paralogues in human: RNU6-1041P (94% identical), RNU6-1316P (82% identical), RNU6-980P (82% identical), RNU6-1145P (80% identical), RNU6-20P (80% identical), RNU6-751P (80% identical), RNU6-1031P (79% identical), RNU6-1036P (79% identical), RNU6-38P (79% identical), RNU6-409P (79% identical), RNU6-589P (79% identical), RNU6-144P (78% identical), and 1285 more.